CFP (complement factor properdin)
Diseases named in the same sentence as CFP in open-access papers (continued):
Sharing a sentence is not in itself a finding about the gene and the disease.
cancer (11 papers, 2013 to 2024). A tumor composed of atypical neoplastic, often pleomorphic cells that invade other tissues. "The higher mRNA expression of CFP was associated with better OS in these cancers, which was also consistent with our results." (PMID 34813686, 2022). "We found that C1ra, C2, and C3 were upregulated in lung fibroblasts incubated with CM of chemotherapy-treated cancer cells, while expression of C5 and CFP was directly upregulated upon incubation with doxorubicin." (PMID 36184683, 2022). "To further evaluate CFP expression in human cancers, we examined RNA-seq data of multiple malignancies in TCGA." (PMID 33976747, 2021). "First, we used PrognoScan to explore the relationship between CFP expression and prognosis of different cancer." (PMID 33976747, 2021). "In this study, the expression pattern and prognostic value of CFP in pan-cancer were analyzed via the Oncomine, PrognoScan, GEPIA and Kaplan-Meier plotters." (PMID 33976747, 2021). "Compared with these studies, our current results indicate that CFP may play a crucial role in the recruitment and regulation of cancer immune infiltrating cells, ultimately affecting the patient prognosis." (PMID 33976747, 2021). "Therefore, future studies are needed to be focus on the mechanism of CFP, at both cellular and molecular levels, will be helpful to clarify the role of CFP in inflammatory and treatment of cancers." (PMID 33976747, 2021). "Similarly, we used the Kaplan Meier plotter to further examine the relationship between CFP and prognosis in different cancers." (PMID 33976747, 2021). "Since TIICs are independent predictors of sentinel lymph node status and survival in cancer, we investigated whether CFP expression correlated with immune infiltration levels in various cancer types." (PMID 33542722, 2020). "Additionally, This study also provided evidence that CFP expression level in cancers are significantly correlated with APCs, APCs can assist and modulate T cell function, speculating whether CFP indirectly affects T cell function through APCs." (PMID 33976747, 2021). "Therefore, CFP could exert an important function in recruitment and regulation of immune infiltrating cells in several carcinomas." (PMID 33542722, 2020). "In Lu and co-workers’ scRNA-Seq dataset (GSE149614), > 66% of macrophages in para-carcinoma tissue expressed CD5L, CETP, MARCO, and CFP, in contrast to < 22% of macrophages in HCC tissue." (PMID 34001107, 2021). "We employed two large-scale bulk HCC RNA-Seq/microarray datasets to compare the expression of HAMP, CD5L, CETP, MARCO, and CFP between HCC and para-carcinoma tissue samples." (PMID 34001107, 2021). "Therefore, a caspase-3 reporter sensor C3 that express the CFP-Asp-Glu-Val-Asp (DEVD)-YFP fusion protein 36, 37 was introduced to cancer cell lines." (PMID 34646378, 2021). "Despite we used the UALCAN database to prove that CFP mRNA and protein expression were uniformly low in LUAD, BRCA, COAD and OV, the relationship between mRNA and protein level in other cancers including STAD could not be proved." (PMID 33976747, 2021). "Similarly, “cancer-specific” escapees generally exhibited higher enrichment at their TSS in the cell lines where they escaped compared to HMECs with a few exceptions (e.g., CFP, FLNA, and MOSPD1 in MDA-MB-436 cells displayed no obvious differences in TSS profiles)." (PMID 25653311, 2015).
blood cancer (2 papers, 2021 to 2023). "Expanding the protein-protein interaction analysis for blood cancers revealed an additional network consisting of CD46, CFP, MASP1 and SERPINE1, correlated with short overall survival." (PMID 36649303, 2023).
CFP also shares sentences with these, for which no sentence is quoted: kidney disease (2 papers); liver cancer (2); sarcoma (2); atypical hemolytic-uremic syndrome (1); bladder cancer (1); brain cancer (1); breast invasive carcinoma (1); clear cell renal cell carcinoma (1); co-infection (1); colorectal cancer (1); Crohn disease (1); cystadenoma (1); demyelination (1); enteritis (1); fibrosarcoma (1); glaucoma (1); glioblastoma (1); glomerulopathy (1); Glucose intolerance (1); Hyperglycemia (1); hyperlipidemia (1); Insulin resistance (1); Kallmann syndrome (1); kidney cancer (1); leukopenia (1); lymphoma (1); mental disorder (1); myeloma (1); neuroblastoma (1); neutropenia (1).
A further 11 diseases each share a sentence with CFP in 1 paper.